TNF (tumor necrosis factor)
Diseases named in the same sentence as TNF in open-access papers (continued):
Sharing a sentence is not in itself a finding about the gene and the disease.
Obesity (continued). "Obesity is a low-grade inflammation that is presented by elevated concentrations of circulating cytokines such as C-reactive protein, tumor necrosis factor-α) and interleukins such as IL-6." (PMID 38243194, 2024). "Elevated systemic pro-inflammatory markers like C-reactive protein, TNF-α, TGF-β, leptin, and IL-6 are linked to the obesity." (PMID 38762465, 2024). "Individuals with obesity display elevated levels of pro-inflammatory cytokines such as interleukin-6 (IL-6) and TNF-α." (PMID 39121085, 2024). "Obesity triggers immune dysfunction characterized by the release of inflammatory adipokines such as TNF-α, IL6, and leptin from adipose tissues." (PMID 38474087, 2024). "Leptin was found to positively correlate with IL-6 and TNFα levels, as well as with clinical parameters of obesity (i.e., body mass index (BMI) and abdominal circumference)." (PMID 38247541, 2024). "To assess the association between chronic low-grade inflammation and obesity, we measured the levels of hs-CRP, IL-6, and TNF-alpha." (PMID 39200519, 2024). "TNF-α plays a major role in adipocyte apoptosis as well as in cellular signaling in obesity-induced inflammation." (PMID 39063610, 2024). "New-onset postoperative obesity was associated with high expressions of CXCL1 (uOR = 3.67; 95% CI, 1.11–12.15; P = 0.034) and TNF (uOR = 2.92; 95% CI, 1.04–9.02; P = 0.045)." (PMID 38965454, 2024). "Regarding metabolic disturbances, it was observed that miR-146a is downregulated in obesity and correlates negatively with IL-6, TNF-α, and CD36." (PMID 38610754, 2024). "Changes in weight loss at the endpoint with total methylation of the TNF-α promoter suggested a putative role of epigenetic regulation of TNF-α expression in subjects with obesity and metabolic syndrome." (PMID 38542788, 2024). "During the same decade, it was reported that adipose tissue secretes tumor necrosis factor-alpha (TNF-α) under conditions of obesity." (PMID 39770983, 2024). "It was shown that in obesity conditions adipocytes are the main producers of transmembrane TNF-α while soluble form of TNF- α is mostly secreted macrophages." (PMID 38572445, 2024). "The increased expression of MAPK, AKT, and TNF proteins was confirmed in the VAT of women with obesity." (PMID 39484291, 2024). "We also examined the levels of inflammatory markers (TNF-α and IL-6), which were selected to assess systemic and hepatic inflammation, as both are known to play significant roles in the pathophysiology of obesity and NAFLD." (PMID 39683472, 2024). "Excess adipose tissue/obesity results in an increased release of various ‘adipocytokines’ like leptin, resistin, tumor necrosis factor-alpha (TNF-α) and interleukin-6 (IL-6)." (PMID 38791525, 2024). "Chronic gastric inflammation in patients with obesity is due to several factors like tumor necrosis factor-α (TNF-α), leptin, and adiponectin." (PMID 39124701, 2024). "Visceral fat acts as an active endocrine tissue, and in patients with obesity or abnormal fat distribution, the secretion of adipose-specific cytokines (leptin, IL-6, TNF-α) is increased." (PMID 39165513, 2024). "Obesity has a significant inflammatory component and overweight individuals have increased serum levels of inflammatory cytokines such as tumor necrosis factor alpha (TNF-α), CRP and interleukins (IL-6, IL-18)." (PMID 38330593, 2024). "According to existing research, obesity induces chronic low-grade inflammation, marked by increased secretion of inflammatory molecules like TNF-α, IL-6, and monocyte chemoattractant protein-1 (MCP-1), primarily by visceral adipose tissue." (PMID 39376657, 2024). "Inflammatory markers associated with obesity, including hs-CRP, IL-6, and TNF-alpha, also demonstrated significantly higher levels in the overweight or obese group." (PMID 39200519, 2024).
Obesity (continued). "In obesity, there is an increased expression of proinflammatory cytokines and hormones that are produced within adipose tissue, such as interleukin-6 (IL-6), tumor necrosis factor-alpha (TNFa), leptin, angiotensinogen, resistin, and C-reactive protein." (PMID 38672532, 2024). "In obesity, dysfunctional adipose tissue releases pro-inflammatory adipocytokines such as TNFα, IL-6, IL-1β, and free fatty acids (FFAs), which increase levels of pro-inflammatory factors." (PMID 39624218, 2024). "LE supplementation not only suppressed obesity-induced skeletal muscle lipid accumulation, but also downregulated TNF-α and atrophic genes." (PMID 38247215, 2024). "As a pro-inflammatory state, Obesity is characterized by elevated levels of inflammatory cytokines such as TNF-alpha, IL-6, and CRP." (PMID 39829729, 2024). "An augmentation in obesity and adipose tissue mass correlates with elevated concentrations of pro-inflammatory cytokines, including TNF-α and IL-6." (PMID 39742290, 2024). "It strongly inhibits the release of pro-inflammatory cytokines such as IL-6 and TNF-α, and helps ameliorate β-cell function, inflammation, and obesity." (PMID 39519546, 2024). "Circulating levels of CTRP12 as well as its mRNA expressions decrease in obesity, in addition to increases in levels of inflammatory markers such as TNF-α in adipocytes." (PMID 39308032, 2024). "In the context of obesity, the presence of macrophage infiltration in AT, can explain the increased level of TNF-α in obese individuals." (PMID 38257150, 2024). "Among the most important are leptin and adiponectin (which, respectively, increase and decrease in obesity), tumor necrosis factor (TNF) α, interleukin (IL)-6, and insulin-like growth factor-1 (IGF-1), CXCL12, steroid hormones, and lipids." (PMID 38339271, 2024). "Upregulated TNF-α in obesity activates the NF-κB pathway via a c-Jun N-terminal kinase-dependent pathway, resulting in downregulated expression of epidermal barrier proteins, including FLG and loricrin (LOR)." (PMID 39564133, 2024). "Previously, we demonstrated that obesity‐induced proinflammatory cytokine (TNF‐α) upregulates AATF expression via SREBP1." (PMID 38558505, 2024). "Low-grade chronic inflammation is linked to obesity; this inflammation is particularly prominent in central and visceral adiposity, which is defined by elevated amounts of CRP, TNF-α, and IL-6." (PMID 38473961, 2024). "TNFα is a cytokine widely utilized as an indicator of the pro-inflammatory state characterizing obesity and contributing to insulin resistance." (PMID 38999869, 2024). "The deleterious effects of TNF-α in inflammatory diseases, including asthma and obesity, are well established." (PMID 38878250, 2024). "Obesity is known to increase proinflammatory cytokines (including interleukin-6 and tumor necrosis factor alpha in the adipose tissue) and leptin (a proinflammatory adipokine) and to decrease adiponectin, leading to dysfunction of innate immunity." (PMID 38557479, 2024). "The state of low-grade inflammation in obesity enhances atherosclerosis, and inflammatory mediators in obesity, such as TNF-α and cfDNA, affect adipocytic Cramp gene expression." (PMID 38474156, 2024). "In obesity, the upregulation of TNF‐α stimulates the activation of inhibitor of IκB kinase (IKK)‐β and MAPKs (such as p38, c‐Jun N‐terminal kinase [JNK], and extracellular signal‐regulated kinase [ERK])." (PMID 38812572, 2024). "Our study revealed that a 6-month curcumin treatment significantly reduced IL-1β, IL-6, and TNF-α in type 2 diabetes patients with obesity." (PMID 39125322, 2024). "Such 3D spheroids outperformed the 2D monolayer adipocytes in responsiveness to fatty acid exposure and TNF-α stimuli for obesity modeling 86,92." (PMID 38505622, 2024). "Obesity is believed to induce a state of chronic inflammation due to adipose tissue releasing pro-inflammatory cytokines such as TNF and IL-6." (PMID 39335469, 2024).
Obesity (continued). "Psoriasis and obesity share some cytokines with proinflammatory activity, like TNF-α, IL-1, and IL-6 and some adipokines (i.e., adiponectin, leptin, resistin, or lipocalin) with a pathogenic role in both diseases." (PMID 39062334, 2024). "Among the most well-studied cytokines concerning obesity are the inflammatory cytokines such as TNF-α (tumor necrosis factor alpha), interleukin-6 (IL-6), and the anti-inflammatory cytokine IL-10." (PMID 39180618, 2024). "Obesity is often characterized by a state of chronic low-grade inflammation, with the increased production of pro-inflammatory cytokines such as tumor necrosis factor-alpha (TNF-α), interleukin-6 (IL-6), and monocyte chemoattractant protein-1 (MCP-1)." (PMID 39765868, 2024). "There were no clear sex differences in cytokine production capacity, although some cytokines were higher in females with obesity compared to males (for IL-1β, IL-6, TNF), in line with findings on activation markers by flow cytometry." (PMID 38741712, 2024). "Higher levels of IL-6 and TNF-α in obesity lead to increased osteoclastogenesis and bone resorption." (PMID 38892923, 2024). "Previous studies have demonstrated the anti-inflammatory activity of CLA, which blunts cytokine release in adipose tissues by inhibiting obesity-induced TNF-α and IL-6." (PMID 38317220, 2024). "Obesity is a clinical manifestation of systemic OS, characterized by elevated levels of proinflammatory cytokines such as TNF-α and IL-6, which contribute to chronic low-grade inflammation." (PMID 38892561, 2024). "It was reported that obesity can induce the inflammatory response in sepsis patients through promoting the overproduction of proinflammatory factors (i.e., tumor necrosis factor)." (PMID 39348397, 2024). "The proinflammatory factors produced by M1-like macrophages, such as TNFα and IL-1β, are increased in islets in obesity and T2DM, and they decrease GSIS by inducing NF-κB or JNK activation in β cells after 16 or 24 h of treatment." (PMID 38693121, 2024). "This is achieved through the upregulation of cytokine production (such as IL-6, TNF-a, etc.)and the recruitment of inflammatory macrophages in obesity mouse model." (PMID 38774876, 2024). "For example, the significance of TNF-α in obesity and NAFLD, as well as IL-6 in diabetes has been reported." (PMID 38504163, 2024). "Further research should be conducted into TNF-α as a biomarker for inflammation related to obesity or T2DM." (PMID 39519417, 2024). "In conclusion, this study demonstrated that three metabolites, PLA, ILA, and LA, highly produced by WiKim39 and WiKim0124, can ameliorate obesity and TNF-α-induced inflammation in hMSCs." (PMID 37940180, 2024). "Our study finely details the VAT transcriptomic profile of patients with obesity, showing the dysregulation of inflammatory pathways, many of which relate to innate immune response and Toll-like receptor, NFκB, and TNF, which are physiologically connected." (PMID 39484291, 2024). "In this study, KITT(iv) was correlated with various clinical parameters associated with obesity and insulin resistance, including VFA, adiponectin, tumor necrosis factor alpha (TNF-α), and BCAA/total AA." (PMID 38905235, 2024). "In obesity, chronic systemic low-grade inflammation is triggered by the release of numerous inflammatory factors, including TNF-α and IL-6, which can activate NF-κB pathway." (PMID 38453770, 2024). "In obesity, Adipose Tissue macrophages polarize into pro-inflammatory M1-like macrophages, secreting various pro-inflammatory cytokines, including tumor necrosis factor (TNF), which impairs insulin signaling and accelerates insulin resistance progression." (PMID 39009585, 2024). "Inflammation is a common link between obesity and cardiometabolic diseases, and TNF-α is one of the main adipokines involved in the inflammatory processes that occur in the context of obesity, mediated by NF-κB, JNK, and NLRP3 inflammasomes." (PMID 38399430, 2024).
Obesity (continued). "Tumor necrosis factor-α (TNF-α), an inflammatory cytokine secreted by adipocytes, has been observed to be elevated in both obesity and GDM." (PMID 39683486, 2024). "A study reported a subsequent decrease in serum CXCL5, HOMA-IR, and TNFα levels in sedentary women with obesity after a 12-week exercise training program." (PMID 39334887, 2024). "These molecules are associated with pro-inflammatory activity and are involved in the development of IR, with elevated circulating levels of TNF-α and IL-6 found in subjects with obesity and IR." (PMID 39310407, 2024). "There is a widespread upregulation of pro-inflammatory signaling cascades in obesity including mediators like IL-6 and TNFα." (PMID 38512816, 2024). "Some components of adipokines, including leptin, adiponectin, resistin, Interleukin-6 (IL-6), and Tumor Necrosis Factor-α (TNF-α), have been associated with the development of insulin resistance, obesity, and related health conditions." (PMID 39457458, 2024). "Obesity is characterized by low-grade chronic inflammation, as adipose tissue, an endocrine organ, secretes cytokines such as IL-6 and TNF-α." (PMID 39588046, 2024). "Macrophage polarization is one of the steps of the inflammatory reaction in obesity and is crucial for the secretion of pro-inflammatory mediators such as TNF-α, IL-6, and MCP-1." (PMID 39063610, 2024). "Previous studies have highlighted the role of pro-inflammatory cytokines, such as IL-6 and TNF-α, as critical mediators in developing insulin resistance and obesity-induced inflammation." (PMID 39513912, 2024). "Obesity induces chronic low-grade inflammation, particularly in visceral fat, which releases inflammatory cytokines such as tumor necrosis factor alpha (TNF-α) and interleukin-6 (IL-6)." (PMID 39684545, 2024). "Deficiency of IFN-γ or its signaling molecule, STAT1, inhibits M1-like macrophage recruitment and TNF-α levels in AT and improves IR with obesity." (PMID 38455510, 2024). "In obesity, macrophages attack AT and increase the release of cytokines such as interleukin-6 (IL-6) and tumor necrosis factor-alpha (TNF-α), leading to inflammation, atherosclerosis, and vascular endothelial dysfunction." (PMID 38629096, 2024). "The performed regression analysis showed that in patients with early stages of CAD, obesity/overweight significantly increased the transcriptional activity of the TNF-α gene." (PMID 39684812, 2024). "Chronic low-grade inflammation, which is in part characterized by the excessive production of pro-inflammatory cytokines, such as TNF-α, IL-1β, IL-12, and IL-6 from expanded WAT, is a key driver of the metabolic dysfunction associated with obesity." (PMID 39684547, 2024). "It was shown that the level of basal secretion of TNF-α in the obesity + CHD group was significantly higher than in control group of normal weight CHD-free participants." (PMID 38572445, 2024). "It has been reported that the proinflammatory factors TNFα and IL-1β are increased and are involved in β-cell dysfunction in obesity and diabetes." (PMID 38693121, 2024). "Adipose tissue releases adipocytokines, including TNF-α, IL-6, leptin, and adiponectin, and elevated serum leptin and reduced serum adiponectin levels are characteristic features of obesity." (PMID 38542720, 2024). "Although the pathogenesis of metabolic syndrome and its links to obesity are not fully understood, it is thought that adipocytokines such as adiponectin, tumour necrosis factor-α (TNF-α), and resistin play a key role." (PMID 38202263, 2024). "Both psoriasis and obesity induce the production of inflammatory markers and mediators, such as TNF-α, and produce pro-inflammatory cytokines, including C-reactive protein and IL-6." (PMID 39200092, 2024). "In the spleen, the major lymphoid organ responsible for systemic immune response, TNF-α and IL-6 expression in this organ decreased significantly with obesity." (PMID 39274918, 2024).
Obesity (continued). "TNF-α downregulated some of the DNA damage repair genes, which are also altered by obesity: PARP1 (−49.3%, P = 0.008), BLM (−46.9%, P = 0.02), FEN1 (−25.5%, P = 0.04), and PCNA (−38.0%, P = 0.008), but did not affect HDAC1 and Ku70 gene expression." (PMID 39092995, 2024). "Several studies in the following years demonstrated that targeting TNF by specific monoclonal antibodies improved insulin sensitivity and improved hepatic steatosis, which is frequently observed in obesity and obese mice." (PMID 38672492, 2024). "Twelve weeks of MICT significantly reduced the levels of inflammatory factors such as interleukin 6 and tumor necrosis factor-α, increase antioxidant capacity and promoted fat metabolism in individuals with obesity." (PMID 39039573, 2024). "We found that Groα/CXCL1 (obesity-associated), MIP-1b/CCL4 (obesity- and HTN-associated), TNFα (HTN-associated), and TGFβ1 and β2 (T2D-associated) were also significantly associated with breast cancer independently." (PMID 38541912, 2024). "African walnuts have been shown to have special bioactive qualities that affect important genes linked to obesity, especially the up‐regulation of PPAR‐γ and adiponectin while down‐regulating TNF‐α, at the molecular level." (PMID 39698791, 2024). "Among chronic disorders, obesity is reported to be a noteworthy promoter of inflammatory status, characterized by an increase in tumor necrosis factor-α (TNF-α), interleukin 6 (IL6), and interleukin 10 (IL10) production." (PMID 38721147, 2024). "In obesity, the levels of chemerin and its receptor CMKLR1 were significantly enhanced, which was associated with inflammation, and TNF-α treatment markedly elevated the chemerin mRNA levels in visceral adipocytes of obese subjects." (PMID 38542187, 2024). "Patients with RA often experience a loss of muscle mass and strength due to chronic inflammation, TNFα overexpression (known as rheumatoid cachexia), joint destruction, obesity, physical inactivity, and age." (PMID 39768307, 2024). "Obesity increases the synthesis and secretion of inflammatory cytokines, such as TNF‐α and free fatty acids, and oxidative stress." (PMID 38501152, 2024). "Individuals with obesity exhibit markedly reduced immunological tolerance, leading to excessive production of inflammatory mediators such as IL-6, TNF-α, IL-1β, and IFN-γ, alongside a significant decrease in anti-inflammatory cytokines like IL-4 and IL-10." (PMID 38840158, 2024). "The proinflammatory cytokine TNF-α has been demonstrated to mediate insulin resistance as a result of obesity in many rodent obesity models." (PMID 39124622, 2024). "In obesity, the increase in adipocyte size is related to the increased release of pro-inflammatory adipocytokines such as tumor necrosis factor (TNF) and interleukin-6 (IL-6)." (PMID 38601207, 2024). "Lipotoxicity triggers the production of TNFα in hepatocytes and obesity enhances its production in liver." (PMID 39514172, 2024). "Apple pectin has been reported to alleviate HFD-induced obesity, attenuate liver steatosis and decrease the level of TNFα and IL6." (PMID 38338579, 2024). "Underlying hypoxemia in OS (originating from OSA, obesity, and COPD) induces the release of systemic inflammatory mediators including C-reactive protein, interleukin-6 and 8, tumor necrosis factor-alpha, and reactive oxygen species." (PMID 39585008, 2024). "There is general agreement that TNF-α and stearate concentrations are mildly elevated in adipose tissue in the state of obesity." (PMID 38928498, 2024). "Increased levels of TNFα and IL-6, commonly encountered in obesity, augment superoxide anion production and nicotinamide adenine dinucleotide phosphate (NADPH) oxidase (NOX) activity." (PMID 38247541, 2024). "Obesity‐induced inflammation activates various signaling pathways, impairs insulin signaling, and promotes the release of proinflammatory mediators such as TNF‐α, IL‐1β, and IL‐6, all of which contribute to IR." (PMID 38812572, 2024).